LRRK2 (leucine rich repeat kinase 2)
Diseases named in the same sentence as LRRK2 in open-access papers (continued):
Sharing a sentence is not in itself a finding about the gene and the disease.
Parkinson disease (continued). "Point mutations in leucine-rich repeat kinase 2 (LRRK2) cause Parkinson’s disease and augment LRRK2’s kinase activity." (PMID 37625589, 2023). "PD patients with LRRK2 mutations showed tremor-predominant parkinsonism, reduced cognitive deficits, and olfactory dysfunctions, but with more depression, anxiety, and irritability." (PMID 37626558, 2023). "We investigated the serum titers and binding characteristics of nAbs-α-Syn in patients suffering from sporadic Parkinson’s disease (n = 38), LRRK2 mutation carriers (n = 25), and healthy controls (n = 22)." (PMID 37759704, 2023). "Pathogenic mutations in LRRK2 kinase cause Parkinson’s disease, and LRRK2 kinase inhibitors are currently in clinical trials in the hopes of benefiting patients." (PMID 37874635, 2023). "Recent work by De Rus Jacuet and colleagues describes co-culture of iPSC-derived brain endothelial-like cells and astrocytes derived from Parkinson’s patients carrying a mutation in LRRK2 in a microfluidic chip." (PMID 38008744, 2023). "The potential Parkinson’s disease importance of microglial LRRK2 is supported by a recent analysis of human genetics data that identified a noncoding LRRK2 variant that confers Parkinson’s disease risk via regulation of LRRK2 expression in microglia." (PMID 37487100, 2023). "The tight association between LRRK2 and Parkinson’s disease has led to a number of in-human clinical trials for both small molecule kinase inhibitors and antisense oligonucleotide gene therapy." (PMID 37986927, 2023). "The prototypical example are some individuals with parkinsonism associated with LRRK2 G2019S or parkin mutation." (PMID 37066922, 2023). "Secondly, the overexpression of LRRK2 causes Parkinson’s-related phenotypes, which are even more severe when the gain-of-function G2019S mutant is expressed." (PMID 37958569, 2023). "The exact cellular function of LRRK2 is not well known, but mutation in LRRK2 (Gly2019Ser) is associated with Parkinson’s disease." (PMID 37047041, 2023). "Mutations that increase the kinase activity of the leucine-rich repeat kinase-2 (LRRK2) represent one of the most common inherited causes of Parkinson’s disease (PD) and have also been linked to inflammatory bowel disease." (PMID 38091401, 2023). "Common LRRK2 mutations associated with Parkinson’s disease include G2019S and I2020T mutations as well as those in the ROC-COR domains." (PMID 37566051, 2023). "A small collection of genes has been linked to Parkinson’s disease including LRRK2, SAT1, and SNCA, the latter of which encodes the protein alpha-synuclein that aggregates in Lewy bodies as a hallmark of the disease." (PMID 36174040, 2022). "A mutation of LRRK2 kinase leads to neurodegenerative disorder diseases such as Parkinson’s disease (PD)." (PMID 36140189, 2022). "Missense mutations in leucine-rich repeat kinase 2 (LRRK2) are the most common cause of familial Parkinson’s disease (PD); however, pathways regulating LRRK2 subcellular localization, function, and turnover are not fully defined." (PMID 35266954, 2022). "The LRRK2 gene is associated with autosomal-dominant, late-onset familial “Parkinson’s disease” (PD)." (PMID 35054514, 2022). "Involvement of astrocytes in Parkinson’s disease came from another study involving mutations in the leucine-rich repeat kinase 2 (LRRK2) protein." (PMID 35336787, 2022). "Recapitulation of the genotype in rodent models causes abnormal dopamine release and increases the susceptibility of dopaminergic neurons to insults, making LRRK2 a valuable model for understanding the pathobiology of Parkinson’s disease." (PMID 35011731, 2022). "Although different gene variants are linked to Parkinson disease, mutations in the Leucine-Rich Repeat Kinase 2 (LRRK2) gene are one of the most frequent causes of Parkinson’s disease related to genetic mutations." (PMID 35743250, 2022). "The G2019S mutation in leucine rich-repeat kinase 2 (LRRK2) is a major cause of familial Parkinson’s disease." (PMID 35453631, 2022).
Parkinson disease (continued). "In the term of genetics, rare variants in the LRRK2 gene are the most common cause of hereditary parkinsonism." (PMID 35054514, 2022). "LRRK2 is a Wnt signaling scaffold protein that has been implicated in the pathogenesis of Parkinson’s disease and mediates canonical Wnt signaling." (PMID 36233336, 2022). "Leucine-rich repeat kinase 2 (LRRK2) gene mutation is an autosomal dominant mutation associated with Parkinson’s disease (PD)." (PMID 36551242, 2022). "Pathogenic mutations in Parkinson's disease enhance LRRK2 protein kinase activity, which stimulates Rab protein phosphorylation." (PMID 36349142, 2022). "VPS35 is an upstream regulator of LRRK2 and, as LRRK2, it is linked to various neurodegenerative diseases including Parkinson’s disease." (PMID 35368245, 2022). "Mutations in Leucine-rich repeat kinase 2 (LRRK2) are the most frequent cause of dominantly inherited Parkinson’s disease (PD)." (PMID 38835904, 2022). "Studies of two mouse models expressing different mutations of the LRRK2 gene, both associated with Parkinson’s disease, reveals distinct alterations at electrochemical, electrophysiological, molecular, and behavioral levels." (PMID 36357506, 2022). "LRRK2 gene is also well known to be a risk gene in Parkinson Disease, and one of the known mutations that confers more risk in that disease has its origin in the Basque population, while that mutation is scarcer in other populations." (PMID 35232999, 2022). "Leucine-rich repeat kinase 2 (LRRK2) is one of the most common causative genes in Parkinson’s disease (PD)." (PMID 35645775, 2022). "The co-occurrence of five variants in LRRK2 gene was more frequent in patients with parkinsonism in Hornacko region." (PMID 35054514, 2022). "Mutations in leucine-rich repeat kinase 2 (LRRK2) cause Parkinson’s disease with a similar clinical presentation and progression to idiopathic Parkinson’s disease, and common variation is linked to disease risk." (PMID 35011731, 2022). "UDCA was also discovered to function as a potential therapeutic agent for Parkinson’s disease by inhibiting leucine-rich repeat kinase 2 (LRRK2) activity and preventing subsequent neuron loss." (PMID 35884899, 2022). "The R1441C mutation in LRRK2 also leads to parkinsonism that is clinically similar to sporadic PD73." (PMID 36114228, 2022). "LRRK1 loss of function mutations cause the bone disorder osteosclerotic metaphyseal dysplasia, whereas LRRK2 missense mutations that enhance kinase activity cause Parkinson's disease." (PMID 36040231, 2022). "Parkinson’s disease has been modeled based on the LRRK2-G2019S mutation seen in sporadic forms, either from carrier-patient-derived iPSC, or iPSC genetically engineered using CRISPR/Cas9 technology." (PMID 36365119, 2022). "Regarding LRRK2, Parkinson’s disease-associated mutation G2019S can promote mitophagy by inducing mitochondrial fission and interacting with ULK1." (PMID 36499214, 2022). "The G2019S mutation in the leucine-rich repeat kinase 2 (LRRK2) gene is associated with late-onset Parkinson’s disease (PD)." (PMID 36671436, 2022). "We further apply PE3 in combination with p53DD to efficiently create multiple isogenic hPSC lines, including lines carrying GBA or LRRK2 mutations associated with Parkinson disease and a LMNA mutation linked to Hutchinson-Gilford progeria syndrome." (PMID 36302757, 2022). "Initially, we chose to target the leucine rich repeat kinase 2 (LRRK2) gene to introduce the G2019S (G6055A) mutation, which is one of the most frequent pathogenic substitutions linked to Parkinson’s disease (PD)." (PMID 36069759, 2022). "Activating mutations in the leucine-rich repeat kinase 2 (LRRK2) cause Parkinson’s disease, and previously we showed that activated LRRK2 phosphorylates a subset of Rab GTPases." (PMID 36149401, 2022).
Parkinson disease (continued). "BIIB122 will also be assessed in a Phase 3 clinical trial NCT05418673, a multicenter, randomized, double-blind, placebo-controlled study of symptomatic Parkinson's disease patients carrying the LRRK2-GS mutation." (PMID 36388213, 2022). "Genetic alterations in the LRRK2 gene, encoding leucine-rich repeat kinase 2, are a common risk factor for Parkinson’s disease." (PMID 36358947, 2022). "In this review, we recapitulate the main LRRK2 pathological mutations that contribute to Parkinson’s disease and the different cellular and therapeutic strategies devised to correct LRRK2 homeostasis." (PMID 35743250, 2022). "The LRRK2 pathogenic mutations as well as overexpression, enhance its kinase activity and lead to cause Parkinson’s disease." (PMID 36590916, 2022). "Missense mutations of leucine-rich repeat kinase 2 (LRRK2), including the G2019S mutant, are responsible for the pathogenesis of Parkinson’s disease." (PMID 36361616, 2022). "Patients with LRRK2 variants show middle- or late-onset parkinsonism with an excellent response to levodopa." (PMID 35720097, 2022). "BDNF genetic polymorphism greatly increases the risk of leucine-rich repeat kinase 2 (LRRK2) in Parkinson’s disease, particularly in subjects with older onset age." (PMID 35743271, 2022). "The aberrant activation of PAK6 in the striata of patients with LRRK2-linked Parkinson’s disease supports the role of PAK6 in the pathogenesis of Parkinson’s disease." (PMID 33306168, 2022). "The leucine-rich-repeat kinase 2 (LRRK2) is a gene associated with Parkinson’s disease (PD), moreover, its kinase activity was found to be upregulated after instigated inflammation of the central nervous system (CNS)." (PMID 36139708, 2022). "Leucine-rich repeat kinase 2/PARK8 (Lrrk2) a gene associated to the neurological disorder Parkinson’s disease was found to be differentially expressed." (PMID 35093178, 2022). "As gain-of-function mutations of LRRK2 are strongly associated with hereditary and sporadic forms of Parkinson disease, LRRK2 kinase inhibition has been pursued as a potential therapeutic strategy." (PMID 36104566, 2022). "Mutations in leucine‐rich repeat kinase 2 (LRRK2), which is known as one of the most common genetic causes of Parkinson's disease (PD), are also suggested as a cause of PSP, although more association studies are required." (PMID 36354133, 2022). "The prevalence of familial and sporadic Parkinsonism due to LRRK2 mutations ranges from 0.1–41%, varying by ethnic population, with the highest prevalence of cases found in patients from North Africa (30–40%) and Ashkenazi Jews (10–20%)." (PMID 35208223, 2022). "Patients with a family history of parkinsonism and LRRK2 G2019S mutation present with characteristic motor features, drug response and clinical course but no α-synuclein positive inclusions in the dopaminergic neurons and neurites in the substantia nigra." (PMID 35965315, 2022). "Genes whose mutations have been associated with parkinsonism include autosomal dominantly (α-synuclein, LRRK2, VPS35, EIF4G1) as well as recessively (PARK2, PINK1, DJ-1, SYNJ1, and PLA2G6) inherited mutations." (PMID 34299248, 2021). "The Parkinson's mutations located within the LRRK2 kinase domain are reported to destabilize the Type-2 conformation in a manner that promotes LRRK2 to adopt its more closed Type-1 conformation." (PMID 33459343, 2021). "RNA sequencing data demonstrate that matrix metallopeptidase 2, which has been shown to degrade extracellular α-syn aggregates, is downregulated in Parkinson's iPSC-derived astrocytes with the LRRK2 G2019S mutation." (PMID 34657636, 2021). "Parkinson’s disease (PD)-linked G2019S mutation of leucine-rich repeat kinase 2 (LRRK2) is known to cause abnormalities in mRNA translation." (PMID 34759048, 2021).
Parkinson disease (continued). "LRRK2 is a large multi-domain protein implicated in ~ 5% of all familial Parkinson’s disease through autosomal-dominant mutations and genetic risk, the most common mutation being the G2019S substitution." (PMID 34530877, 2021). "In contrast, autosomal dominant missense mutations located within the GTPase or kinase catalytic domains that hyperactivate LRRK2 protein kinase activity, are one of the most common causes of inherited Parkinson's disease." (PMID 33459343, 2021). "Here, we study the basic neurobiology of VPS35 and Parkinson’s disease mutation effects in the D620N knock-in mouse and the effect of leucine-rich repeat kinase 2 (LRRK2) inhibition on synaptic phenotypes." (PMID 34530877, 2021). "To probe the role of disease-associated mutations in LRRK2, we used flies expressing Lrrk with mutations homologous to Parkinson disease-associated mutations in human LRRK2." (PMID 34030727, 2021). "Autosomal dominant mutations in LRRK2 are one of the most common monogenic forms of Parkinson’s disease (PD) accounting for 1–2% of all PD patients." (PMID 33800548, 2021). "LRRK2, Leucine-rich repeat kinase 2, mutations are the most common cause of familial Parkinson’s disease and are an important risk factor for apparently sporadic disease." (PMID 34030727, 2021). "Core features of LRRK2 G2019S-associated PD include asymmetrical, tremor-predominant parkinsonism with bradykinesia, and rigidity that respond to dopamine replacement and functional neurosurgery." (PMID 33805527, 2021). "Heterozygous gain-of-kinase function variants in LRRK2 (leucine-rich repeat kinase 2) cause 1–2% of all cases of Parkinson’s disease (PD) albeit with incomplete and age-dependent penetrance." (PMID 34125248, 2021). "To achieve a mechanistic understanding of LRRK2, a multidomain protein kinase, we must understand how the conformational landscape is changed by specific mutations that cause LRRK2 to become a driver of Parkinson’s disease (PD)." (PMID 34088839, 2021). "An ASO designed to induce the skipping of exon 41 of LRRK2, which encodes part of the kinase domain, was developed to reduce LRRK2 kinase function in patients with genetic and sporadic Parkinson’s disease." (PMID 34414317, 2021). "Activating LRRK2 mutations cause Parkinson’s disease, and pathogenic LRRK2 kinase interferes with ciliogenesis." (PMID 34658337, 2021). "The Parkinson's causing VPS35[D620N] mutation markedly enhances LRRK2-mediated Rab protein phosphorylation." (PMID 33459343, 2021). "In previous studies of Parkinson’s disease, LRRK2 was found to be associated with changes in the cytoskeleton." (PMID 35345836, 2021). "Although there is some variability in experimental results across the LRRK2 literature, most studies suggest that Parkinson’s disease-promoting mutations in the GTPase domain decrease the GTPase activity of LRRK2 and increase the proportion of GTP-bound LRRK2." (PMID 34030727, 2021). "To explore how pathogenic mutations of the multidomain leucine-rich repeat kinase 2 (LRRK2) hijack its finely tuned activation process and drive Parkinson’s disease (PD), we used a multitiered approach." (PMID 34088839, 2021). "In this context, Manolio and colleagues conveniently classified LRRK2 as a high penetrant gene associated with Parkinson disease with G2019S mutation being the main cause of Parkinson familial cases." (PMID 34490083, 2021). "These proteins interact with LRRK2, which is a gene that has been independently associated with leprosy, and Parkinson’s disease." (PMID 33936067, 2021). "Autosomal dominant mutations that activate the LRRK2 (leucine rich repeat protein kinase-2) signaling pathway cause late-onset Parkinson's disease." (PMID 34515301, 2021). "Leucine-rich repeat kinase 2 (LRRK2) has emerged from GWAS as one of the most important risk loci for Parkinson's disease." (PMID 34335440, 2021).
Parkinson disease (continued). "Dominant mutations in the leucine-rich repeat kinase 2 (LRRK2) gene are the most common genetic cause of familial Parkinson’s disease (PD), with the G2019S missense mutation being most frequent disease-causing mutation in LRRK2." (PMID 34759048, 2021). "Mutations in the Parkinson’s disease (PD) protein Leucine Rich Repeat Kinase 2 (LRRK2) have been under study for more than 15 years and our understanding of the cellular phenotypes for the pathogenic mutant forms of LRRK2 has significantly advanced." (PMID 33922322, 2021). "Parkinson’s-disease-associated LRRK2 is a multidomain Ser/Thr kinase that phosphorylates a subset of Rab GTPases to control their effector functions." (PMID 33887226, 2021). "A common theme throughout some of the PSP/parkinsonism cases reported with an LRRK2 mutation was unresponsiveness to levodopa, differing from a regular PD diagnosis." (PMID 34360863, 2021). "We first confirmed that Lrrk containing a mutation (Lrrk-R1069C) homologous to the Parkinson’s disease-promoting Roc GTPase mutation LRRK2-R1441C enhanced the toxicity of transgenic human α-synuclein." (PMID 34030727, 2021). "Missense mutations in the LRRK2 gene were first identified as a pathogenic cause of Parkinson’s disease (PD) in 2004." (PMID 33494262, 2021). "The dominant gain-of-function mutation in LRRK2 is challenging for the treatment of parkinsonism by gene silencing or gene disruption strategies because LRRK2 plays pivotal roles in many regulatory pathways, including the immune system." (PMID 34551822, 2021). "Some of the strongest disease associated genes in Parkinson's disease encode for kinases; LRRK2 and PINK1." (PMID 33642997, 2021). "LRRK2 is associated with both the familial and sporadic forms of Parkinson's disease, with G2019S being the most common mutation, which increases its kinase activity." (PMID 34335440, 2021). "Abnormalities in LRRK2 cause F-actin hyperstabilization and Drp1 mislocalization, which induce neurotoxicity of the microtubule-binding protein Tau in Parkinson’s disease." (PMID 34741026, 2021). "Recent tomography and cryo-EM analysis provide the first glimpse of the LRRK2 structure revealing how Parkinson's mutations and inhibitors modulate the closed and open conformation of the kinase and impact upon microtubule binding." (PMID 33367571, 2021). "Sporadic Parkinson's Disease was modeled in midbrain organoids generated from patients carrying a mutation in the LRRK2 gene and compared to isogenic controls." (PMID 34483818, 2021). "The p.G2019S coding variant in the LRRK2 (leucine-rich repeat kinase 2) gene is the commonest high penetrance mutation causing parkinsonism." (PMID 32873436, 2021). "Patients with LRRK2 variants showed middle- or late-onset Parkinsonism, a good response to levodopa, and few complications associated with cognitive decline." (PMID 33918221, 2021). "Examples are PICALM/CALM contributing to Alzheimer’s disease pathology, C9ORF72 implicated in ALS and FTD and several genes linked to Parkinson’s disease such as LRRK2, VPS35, SNCA, Synj1 and EndoA." (PMID 34988081, 2021). "We identify two LRRK1 mutations (K746G and I1412T), equivalent to the LRRK2 R1441G and I2020T Parkinson's mutations, that enhance LRRK1 mediated phosphorylation of Rab7A." (PMID 33459343, 2021). "Variants in the leucine-rich repeat kinase 2 (LRRK2) gene are associated with increased risk for familial and sporadic Parkinson’s disease (PD)." (PMID 34145320, 2021). "Mutations in genes encoding either PINK1 or Parkin are implicated in the pathogenesis connected with Parkinson’s disease along with mutations to LRRK2 (leucine-rich repeat kinase 2), which is also found in the OMM." (PMID 33498615, 2021). "One of the main genes of the familial form of Parkinson’s disease is the LRRK2 gene, which encodes a leucine-rich protein kinase, dardarin." (PMID 34421573, 2021).